PIK3CA (phosphatidylinositol-4,5-bisphosphate 3-kinase catalytic subunit alpha)
Diseases named in the same sentence as PIK3CA in open-access papers (continued):
Sharing a sentence is not in itself a finding about the gene and the disease.
cancer (continued). "This cluster contained mutations in representative cancer-associated genes such as KRAS, ARID1A, PIK3CA, and FBXW7." (PMID 40679511, 2025). "Based in treatment options for other cancers, we identified some potential targetable genomic alterations such as PIK3CA and EGFR to help the selection of patients with PSCC for future clinical trials with targeted therapies including Alpelisib and Cetuximab." (PMID 39222919, 2025). "Overall, some COSMIC genes such as PIK3CA, show that a consistent set of regulators (i.e. TFs and lncRNAs) predict PIK3CA expression across cancers." (PMID 40041206, 2025). "In adenomyotic epithelium, we identified somatic mutations in cancer-associated genes such as KRAS (34.1%), PIK3CA (12.2%), ARID1A (12.1%), and FBXW7 (9.8%) with high mutant allele frequency." (PMID 40679511, 2025). "Patients with AKT mutations will be assigned to capivasertib, while taselisib and copanlisib will target PIK3CA or PTEN mutant cancers." (PMID 39808497, 2025). "Alterations in PI3K pathway genes—including PIK3CA, PTEN, AKT1/2/3, TSC1/2, MTOR, and RICTOR—are frequent in CRC and have been associated with chemotherapy resistance and poor prognosis in other cancers." (PMID 41301724, 2025). "Network pharmacology identified 427 potential targets for 12 bioactive alkaloids, with core targets (PIK3CA, PIK3CD, MAPK8, and JAK2) implicated in cancer-related pathways such as PI3K-Akt signaling." (PMID 41169715, 2025). "Additionally, examining how PIK3CA mutations may modulate treatment response, particularly to temozolomide, is critical, given the current evidence of these mutations conferring resistance to multiple therapeutic strategies in other cancers." (PMID 40508087, 2025). "In CRC, the most common genetic alterations include IGF2 overexpression, PIK3CA mutations, and PTEN mutations or deletions, with these changes present in approximately 40% of malignant tumors." (PMID 40165548, 2025). "We found 6 significant gene-cancer type pairs impacted by CNAs where samples also contained eccDNA copies of the gene, including PIK3CA in BRCA, KRAS in COAD and LUAD, BRAF in SKCM, and EGFR in LUAD." (PMID 41415395, 2025). "PIK3CA gene encodes the catalytic subunit alpha (p110α) of phosphatidylinositol 3-kinase (PI3K), which is frequently mutated in human cancers, especially in breast cancer." (PMID 40303291, 2025). "The physiological function of the IR-PI3K-AKT pathway is regulating blood glucose levels, and PIK3CA mutations activate the PI3K pathway and fuel cancer by promoting glucose uptake and accelerating glycolytic flux." (PMID 39717717, 2025). "Almost all PIK3CA mutations are associated with an elevation of lipid kinase activity in CRC and promote cancer cell proliferation, survival and other malignant behaviors." (PMID 38848145, 2024). "This comparison confirmed that the PIK3CA cancer hotspot sites, glutamic acid residues, p.E542 and p.E545, naturally mimic the phosphotyrosine residues that most SH2 domains require for specific binding." (PMID 38541623, 2024).
cancer (continued). "In contrast, activating PIK3CA gene alterations, present in 18 cases (2% of the entire cohort), were distributed across cancer diagnoses with 6 different extracranial solid tumors and 5 different CNS solid tumor diagnoses containing these alterations." (PMID 38992034, 2024). "In light of the successful genetic analysis of oncogenic point mutations in the KRAS, PIK3CA, and IDH1 genes of human cancer cell lines using RGEN-RFLP, it can be inferred that WD diagnosis should be possible by using this method." (PMID 39056796, 2024). "The cancer hotspots lose their phosphomimetic nature with a charge reversal, negating the binding of PIK3CA and PIK3R1 through this domain." (PMID 38541623, 2024). "This concomitant association between PIK3CA mutations and other oncogenic mutations, such as RAS or EGFR mutations, has important implications for the treatment of cancer." (PMID 38616230, 2024). "By cross-referencing these sources, we identified five top oncogenes—ALK, EGFR, GNAS, KRAS, and PIK3CA —due to their frequent occurrence and their critical roles in multiple cancers." (PMID 39684787, 2024). "The genetic variants p.R409Q (described in cancer) and p.N564D (described in cancer and vascular/overgrowth) had interaction energy that resulted in the former destabilizing the binding to PIK3CA and the latter stabilizing the binding significantly." (PMID 38541623, 2024). "Somatic mutations have been identified in numerous genes, including PIK3CA, PTEN, Akt1 and other members of the PI3K-AKT-mTOR pathway, many of which have been clearly demonstrated to play important roles in promoting cancer cell proliferation and survival." (PMID 38616230, 2024). "The interplay between PIK3CA alterations and the acquisition of migratory and invasive phenotypes in TNBC cells is a focal point in cancer research, offering insights into the underlying mechanisms of metastasis." (PMID 39369580, 2024). "In the comprehensive cohort analysis, PIK3CA exon 9 and 20 mutations were overrepresented in proximal colon cancer, CIMP-low (CIMP-L), and KRAS-mutated cancers." (PMID 39113889, 2024). "PIK3CA mutations occur in various cancers, at frequencies of 5% to 8% in NSCLC cases and have been identified in approximately 6.33% of Chinese pan-cancer samples." (PMID 39743996, 2024). "The results showed that GluOC inhibited the apoptosis of cancer cells via the ROCK1/JAK2/PIK3CA/AKT signalling pathway, promoted cell cycle progression, reduced ROS levels during cancer cell death, and promoted an increase in stem cell properties." (PMID 39054484, 2024). "This study demonstrates the clinical relevance of PIK3CA and SOX2 amplification in laryngeal tumorigenesis as early cancer risk markers beyond current histopathological grading." (PMID 38473941, 2024). "Associations with SPTA1, PIK3CA, and MAP3K1 mutations suggest the role of DDIT3 in diverse pathways in cancer progression." (PMID 38911383, 2024).
cancer (continued). "Cancer subtypes with G12/13 prevalence in the concordantly upregulated axes are characterized by mutations of the KRAS, PIK3CA, and MLLT3 oncogenes." (PMID 38723607, 2024). "This study applied AutoEpiCollect’s final vaccine design to develop a pan-cancer vaccine targeting the PIK3CA gene." (PMID 38671743, 2024). "Preclinical studies of KRAS- and BRAF-mutated CRC noticed the necessity of dual inhibition of MEK and PIK3CA pathways in the animal model of cancer." (PMID 39056802, 2024). "Mutations in the PI3K signaling pathway pose a significant challenge to the efficacy of PI3K inhibitors in cancer therapy, particularly secondary to key components such as the PIK3CA gene and other essential components of the signaling pathway." (PMID 38172946, 2024). "Among 13 luminal B samples, two tumors presented just one cancer driver, i.e., PIK3CA (oncogene) in one of the tumors, and AKT1 (oncogene) in the other." (PMID 39208653, 2024). "AutoEpiCollect and our PIK3CA pan-cancer vaccine data should be used in future murine model trials to test the efficacy of our novel vaccine design and strengthen future epitope selection methods." (PMID 38671743, 2024). "Among them, GEO data analysis showed that PIK3CA was the only up-regulated mRNA, with increased expression in cancer tissues and higher expression in advanced stage EC than in early stage EC." (PMID 38784043, 2024). "Alterations in this pathway, often stemming from gene mutations in PIK3CA and loss of PTEN, significantly contribute to cancer initiation, progression, and resistance to therapeutic agents." (PMID 38562143, 2024). "In a group of 587 studied patients with epithelial ovarian cancer, SNPs at PIK3CA rs9838117 and ERBB2 rs1058808 loci associated with cancer cell signaling were found to be correlated with the risk of cancer." (PMID 38275400, 2024). "Pathway analysis using GO, KEGG, and Reactome further narrowed down potential molecular targets, showing notable associations with apoptosis signaling pathways in cancer, particularly for HSP90AA1, MAPK1, and PIK3CA." (PMID 39518920, 2024). "The PIK3CA gene highly amplified in gastric, prostate, thyroid, ovarian, cervical, and several other cancers." (PMID 38336976, 2024). "For example, mutations in PIK3CA and PTEN are frequently observed in several cancer types, and these mutations lead to activation of the PI3K/AKT/mTOR pathway, thus promoting cell survival and growth." (PMID 38669103, 2024). "An array of cancers harboring oncogenic alterations of PIK3CA, KRAS, PTEN, EGFR, and RHOA have been reported to be associated with activated PI3K/AKT-mTOR signaling." (PMID 39164472, 2024). "Phosphatidylinositol-4,5-bisphosphate 3-kinase catalytic subunit alpha [PIK3CA, encoding PI3Kalpha (also known as p110α)] is one of the most commonly aberrated genes in human cancers." (PMID 39543937, 2024). "It has been reported that the most mutated and amplified oncogene in human cancers, including HNSCC, is PI3K catalytic subunit alpha isoform (PIK3CA), the gene that programs for the p110a isoform of PI3K." (PMID 39062182, 2024). "PIK3CA gene mutations can lead to the overactivity of the PI3K enzyme, promoting the growth of cancer cells." (PMID 39126074, 2024).
cancer (continued). "Somatic mutations in key members of this signaling pathway, including PIK3CA, PIK3R1 and AKT, are known to be among the main causes of cancer." (PMID 38616230, 2024). "PIK3CA gene variations play a crucial role in cancer development and are frequently detected across various cancer types." (PMID 39685930, 2024). "Somatic mutations in the PIK3CA gene that encodes the subunit p110 of class I PI3K, as well as PTEN mutations resulting in PTEN silencing, are the most prominent in cancer." (PMID 38672636, 2024). "In recent years, there has been a growing body of evidence indicating the presence of somatic mutations in cancer-associated genes including ARID1A, PIK3CA, KRAS, or PPP2R1A in endometriotic lesions." (PMID 38600147, 2024). "It is a pan-cancer mutagen; therefore, studying PIK3CA is more conducive to the development of clinical drugs." (PMID 39493752, 2024). "PIK3CA mutations are present in 15–20% of CRC entities and play a key role in cancer development and progression, as we describe further in the following paragraphs." (PMID 38791445, 2024). "Among them, two patients are currently under evaluation for subsequent treatment (PIK3CA assessment), and four patients probably switched to a different cancer center." (PMID 38912058, 2024). "The combination of alpelisib and capecitabine is generally tolerated, without pharmacokinetic interactions, and shows antitumor activity in patients with PIK3CA mutant advanced cancers." (PMID 39070139, 2024). "Taking advantages of these differences, the authors performed RNA-Seq on PIK3CA WT and mutant tumors and identified an enrichment of the neutrophil chemoattractant IL-8 in PIK3CA-mutant cancer cells." (PMID 38426501, 2024). "Screening for PIK3CA mutations is mandatorily recommended when considering patient candidates for PI3K inhibitor-targeted therapy, especially for cancers with endocrine resistance." (PMID 39197004, 2024). "Our results for H2L carcinomas are consistent with these reports, showing a rather low-grade clinicopathological profile of PIK3CA-mutant H2L carcinomas, similar to that of HER2-negative carcinomas." (PMID 38893129, 2024). "These alterations, including oncogenic mutations in PIK3CA and IDH2, have already been categorized as Level 1 alterations in other cancer types, but are still emerging as potential therapeutic targets in NSCLC." (PMID 38155717, 2023). "These alkylating signatures targeted cancer driver mutations KRAS p.G12D, KRAS p.G13D, and PIK3CA p.E545K, as well as predicted poor survival in CRC patients." (PMID 37525147, 2023). "In this study, we investigate the efficacy of MEN1611 in models of NSCLC with a wild-type PIK3CA gene using in vitro studies on cancer cell lines and in vivo xenograft murine models." (PMID 38033496, 2023). "At the COSMIC Cancer Gene Census gene level, CACNA1D, PIK3CA, and WNK2 mutations belonged to the dMMR-like type of NECC." (PMID 37920164, 2023).
cancer (continued). "We determined the incidence and type of all somatic PIK3CA and PIK3R1 mutations by whole exome sequencing (WES) in a pan-cancer cohort of 1200 patients." (PMID 36934165, 2023). "Loss or alteration of PTEN or PIK3CA often results in hyperactive signaling of the PI3K‐Akt pathway, leading to an aggressive cancer phenotype." (PMID 36573306, 2023). "Among these (e.g., patients 16–24), some were indeed cancer cells that displayed point mutations in the KRAS and PIK3CA genes (Pt." (PMID 36672711, 2023). "Among these features, genomic markers are closely related to mutations and cancer metastasis, with BRCA1, BRCA2, and PIK3CA being previous impact markers." (PMID 36765522, 2023). "Here, we describe the different PIK3CA and PIK3R1 mutations observed in a real-life cohort of 1200 cancer patients." (PMID 36934165, 2023). "A previous study demonstrated a key role for PIK3CA in driving epithelial-to-mesenchymal transition and cancer stem cell phenotypes during cancer progression." (PMID 36645186, 2023). "It has recently been reported that pathogenic PIK3CA variants causing PROS are spread along the entire gene, but that the three hotspots most commonly mutated in cancer are involved in >50% of cases." (PMID 38136956, 2023). "When we limited the analysis to the genes of the COSMIC Cancer Gene Census Tier 1, only four genes, including ATP2B3, CACNA1D, KRAS, and PIK3CA, showed recurrent mutations only in two patients." (PMID 37920164, 2023). "In our study, we found that cancer cells display distinct oncogenic alterations in the two risk groups (e.g., KRAS, PIK3CA, mTOR) that appear to directly induce metabolic changes." (PMID 36671486, 2023). "The pathway, with oncogene PIK3CA and tumor suppressor gene PTEN, is implicated in the sensitivity of cancer tumors to insulin and IGF-1." (PMID 37446128, 2023). "The PIK3CA variants in PROS, including KTS, have a similar profile to that in cancers, and an association of hotspot variants with more severe hypertrophy has been suggested, with milder hypertrophy linked to rarer non-hotspot variants." (PMID 37667289, 2023). "For instance, AR-42 and belinostat were found significantly associated with PIK3CA mutation in HNSC + LUSC (here considered jointly because of known molecular similarities of the cancer types), in BRCA, and in LUAD cancer types." (PMID 37095494, 2023). "PIK3CA gene, encoding the catalytic subunit of PI3K, is one of the most frequently mutated genes in cancer." (PMID 37277821, 2023). "KMT2D and GATA3 were uniquely identified in African Americans as cancer drivers reported in TCGA data, whereas PIK3CA, MAP3K1, CDH1, and MUC6 were identified in Caucasians." (PMID 37454130, 2023).